MFSD2A (MFSD2 lysolipid transporter A, lysophospholipid)
Diseases named in the same sentence as MFSD2A in open-access papers (continued):
Sharing a sentence is not in itself a finding about the gene and the disease.
diabetic retinopathy (3 papers, 2023 to 2024). "Mfsd2a downregulation was also reported in diabetic retinopathy and was associated with the upregulation of the Srebp signaling pathway, that was previously observed in the eyes of Mfsd2a knockout mice." (PMID 39273347, 2024). "Similarly, Mfsd2a downregulation in diabetic retinopathy was associated with the upregulation of Srebps." (PMID 37762391, 2023). "Therefore, we suggest that enriching retinal DHA through dietary LPC-EPA/DHA, the preferred substrate for Mfsd2a, may prove beneficial in the prevention of diabetic retinopathy." (PMID 39728692, 2024).
gestational diabetes (3 papers, 2020 to 2024). Carbohydrate intolerance first diagnosed during pregnancy. "The expression of Mfsd2a has also been shown to be decreased in the placenta in gestational diabetes." (PMID 39728692, 2024). "This is consistent with previous findings that high maternal DHA levels were associated with low MFSD2a in the placenta, and it is perhaps why we see decreased DHA in the cord blood of women with gestational diabetes." (PMID 37106728, 2023). "Therefore, more attainable biological samples, such as the blood, would represent a more suitable alternative for the study of MFSD2a and many other molecules that may be used as proteomic biomarkers for the clinical evaluation of gestational diabetes mellitus." (PMID 32117064, 2020).
hepatocellular carcinoma (3 papers, 2019 to 2023). A malignant tumor that arises from hepatocytes. "To test this idea, we generated a human hepatoma cell line using HuH-7 cells that stably express a Mfsd2a-GFP fusion protein." (PMID 37463052, 2023). "Other studies have shown that MFSD2A+ is expressed in many tissues (especially in the liver) and is not only significantly downregulated in hepatocellular carcinoma but also able to repopulate the liver during hepatocyte regeneration." (PMID 36389730, 2022). "Relationship between MFSD2A expression and clinicopathological features of hepatocellular carcinoma patients." (PMID 31584009, 2019). "In summary, our results showed that MFSD2A expression is downregulated in hepatocellular carcinoma." (PMID 31584009, 2019).
Stroke (3 papers, 2022 to 2026). Sudden impairment of blood flow to a part of the brain due to occlusion or rupture of an artery to the brain. "Given the core role of Mfsd2a in stroke pathology, targeting this molecule essentially aims to repair the multifunctional protective system proposed in our framework, which has collapsed because of its downregulation." (PMID 41358569, 2025). "The pathophysiology of Mfsd2a dysfunction in stroke extends beyond the increase in transcytosis inhibition." (PMID 41358569, 2025). "Critically, the disruption of Mfsd2a function, as occurs during stroke, compromises this vital support system for the paracellular seal." (PMID 41358569, 2025). "In stroke, the significant downregulation of Mfsd2a protein and mRNA expression reverses this suppression." (PMID 41358569, 2025). "Perhaps the most therapeutically relevant function of Mfsd2a in stroke is its role as a master inhibitor of caveolae‐mediated transcytosis." (PMID 41358569, 2025). "The unifying framework proposed earlier in the introduction section—positioning Mfsd2a as a central node in stroke pathology—rests upon its fundamental biological roles." (PMID 41358569, 2025). "To further understand the molecular mechanisms of Storax regulating caveolae-mediated transcytosis after stroke, we examined Cav-1, Mfsd2a, AQP4, and PDGFR-β expressions by Western blotting." (PMID 35873558, 2022). "The downstream consequences of impaired Mfsd2a‐mediated DHA transport are twofold and highly relevant to stroke pathology." (PMID 41358569, 2025). "In this context, Mfsd2a as a key molecule in BBB endothelial cells, provides a novel approach for stroke treatment through its functional regulation." (PMID 41358569, 2025). "We also found that Storax has effects in decreasing the expression of Cav-1 and AQP4 and increasing the expression of Mfsd2a and PDGFR-β at 6 h after stroke." (PMID 35873558, 2022). "Because the transport of LPC‐DHA by Mfsd2a is the basis for its function, increasing the supply of the substrate LPC‐DHA can theoretically increase its transport efficiency and play a role in the prevention and treatment of stroke." (PMID 41358569, 2025).
brain tumor (2 papers, 2018 to 2021). "We show that Mfsd2a expression as well as its transport functions are selectively down regulated in the metastatic brain tumor vascular endothelium." (PMID 29844613, 2018).
colitis (2 papers, 2021 to 2023). Inflammation of the colon. "Besides, DHA-derived epoxides can restore the ability of the endothelium to resolve intestinal inflammation through major facilitator superfamily domain containing 2A (MFSD2A), and overexpression of MFSD2A reduces colitis in mice." (PMID 37868958, 2023). "In addition, MFSD2A was shown to reduce colitis in mice through ω-3 docosahexaenoic acid-induced metabolism in the gut vasculature." (PMID 33760887, 2021).
fatty liver (2 papers, 2020 to 2022). "In contrast, major facilitator super family domain containing 2a (MFSD2A) is a key transporter for ω3 FAs which is essential for the prevention of fatty liver." (PMID 35614477, 2022).
gastric cancer (2 papers, 2021 to 2025). A primary or metastatic malignant neoplasm involving the stomach. "MFSD2A, another target of miR-212-5p, has been shown to have beneficial effects in gastric cancer." (PMID 33760887, 2021).
gestational hypertension (2 papers, 2023 to 2024). "A potential role for MFSD2a as a DHA transporter in the placenta has been suggested in pregnancies complicated by GDM and preeclampsia in which maternal DHA and cord blood DHA are not well correlated." (PMID 38068814, 2023).
intracerebral hemorrhage (2 papers, 2021). A cerebrovascular disorder characterized by bleeding into one or both cerebral hemispheres including the basal ganglia and the cerebral cortex. "That said, while Mfsd2a levels are generally decreased in acute conditions such as intracerebral hemorrhage, Mfsd2a has been shown to be largely upregulated in more chronic disorders such as chronic liver injury and inflammatory bowel disease." (PMID 34702292, 2021). "Mfsd2a may protect BBB by inhibiting vesicle endocytosis after intracerebral hemorrhage." (PMID 34566571, 2021).
ischemic stroke (2 papers, 2022 to 2025). A stroke disorder caused by obstruction of blood flow to the brain, due to thrombotic (local blood clot formation) or embolic (due to a blood clot or other material traveling from another site) event. "This collective body of work firmly positions Mfsd2a as a promising and legitimate target for future therapeutic exploration in ischemic stroke." (PMID 41358569, 2025). "In conclusion, although the preclinical portfolio of direct Mfsd2a intervention in ischemic stroke is still in its early stages, the existing evidence is compelling." (PMID 41358569, 2025). "This review aims to elucidate the role of Mfsd2a in ischemic stroke pathophysiology and evaluate the therapeutic potential of strategies targeting its function." (PMID 41358569, 2025). "This review proposes a unifying framework that positions Mfsd2a as a central indicator of ischemic stroke pathophysiology and a potential target for treatment." (PMID 41358569, 2025). "We also propose a unifying framework in which Mfsd2a serves as a central node in ischemic stroke pathology." (PMID 41358569, 2025). "In summary, the role of Mfsd2a in ischemic stroke is multifaceted but centered on its core function as a guardian of the BBB." (PMID 41358569, 2025). "This study provides a critical theoretical basis for pharmacological targeting of the Mfsd2a pathway as a beneficial strategy in ischemic stroke." (PMID 41358569, 2025). "The indispensability of these integrated physiological functions makes Mfsd2a a compelling target in ischemic stroke." (PMID 41358569, 2025). "Following ischemic stroke (right), Mfsd2a expression is downregulated, leading to increased caveolae formation, disruption of tight junctions, BBB breakdown, and enhanced neuroinflammation." (PMID 41358569, 2025). "The significant downregulation of Mfsd2a expression after ischemic stroke is a key pathological link leading to BBB destruction, brain edema, intensified neuroinflammation and nerve injury." (PMID 41358569, 2025). "While the ability of Mfsd2a to suppress transcytosis is a universal principle of BBB maintenance, its paramount importance in ischemic stroke is highlighted by the acute and explosive nature of caveolae‐mediated transcytosis activation in this context." (PMID 41358569, 2025). "This graphical abstract illustrates the central role of Mfsd2a in maintaining blood–brain barrier (BBB) integrity under physiological conditions and its dysregulation following ischemic stroke." (PMID 41358569, 2025). "Targeting Mfsd2a shows a promising therapeutic strategy to protect the BBB and improve neurological outcomes after ischemic stroke." (PMID 41358569, 2025). "The consistent success of Mfsd2a‐targeted interventions in stabilizing the BBB across ICH, SAH, and other models, despite differing initial insults, provides robust indirect support for its therapeutic applicability in ischemic stroke." (PMID 41358569, 2025). "The results illustrated that the major transcellular proteins, Cav-1, Mfsd2a, and AQP4, have been changed and led to increasing transcellular permeability at the early stage of ischemic stroke, while the TJ proteins are not significantly altered or dysregulated." (PMID 35873558, 2022).
lung adenocarcinoma (2 papers, 2010 to 2019). A carcinoma that arises from the lung and is characterized by the presence of malignant glandular epithelial cells. "Here we show that MFSD2A expression is strongly downregulated in non-small cell lung cancer cell lines of different histotypes and in primary lung adenocarcinomas." (PMID 20236515, 2010). "Additionally, recent study revealed that DAPK2, MFSD2A, THSD1 and WNT7A were oncogenes which showed high expression and low methylation in lung adenocarcinoma." (PMID 30899432, 2019).
non-alcoholic steatohepatitis (2 papers, 2023 to 2024). "Mfsd2a liver-specific deficiency in mice (L2aKO) led to a robust nonalcoholic steatohepatitis–like (NASH-like) phenotype within just 2 weeks of dietary fat challenge associated with reduced hepatic phospholipids containing linoleic acid." (PMID 37463052, 2023). "The up- or downregulation of additional genes that showed sex-specific responses (G0s2, Igfbp1, Mfsd2a, Myc, and Tat), as observed in the male rats, has been reported to increase lipid accumulation and lead to a non-alcoholic steatohepatitis-like phenotype." (PMID 38903859, 2024).
non-small cell lung carcinoma (2 papers, 2010 to 2011). A group of at least three distinct histological types of lung cancer, including non-small cell squamous cell carcinoma, adenocarcinoma, and large cell carcinoma. "The MFSD2A gene was also strongly downregulated in a panel of non-small cell lung cancer (NSCLC) cell lines, where it inhibits cell adhesion and migration when overexpressed." (PMID 21736709, 2011).
retinal degeneration (2 papers, 2018 to 2021). Degeneration of the retina. "However, no change was observed in Mfsd2a expression, the deficiency of which causes retinal degeneration via decreased DHA trafficking." (PMID 33963174, 2021).
aneurysm (1 paper, 2019). Bulging or ballooning in an area of an artery secondary to arterial wall weakening. "We selected and validated the genes randomly (Lrrc17, Gxylt2, Mfsd2a, Scube and Ank2) and based on their role in aneurysms (Mmp12, Spp1, Ctss) or cardiovascular complications (Mfap4, Igfbp2) or inflammatory signalling pathways (Ccls and Ccrs)." (PMID 30677223, 2019).
Ataxia (1 paper, 2012). Ataxia refers to impaired coordination of voluntary muscle movement. "Based on prominent hyperactivity and ataxia, as well as the small body size and early post-natal death of Mfsd2a KO mice, it is likely that MFSD2A plays a profound role in brain metabolism." (PMID 23209793, 2012). "Mfsd2a knockout mice have normal liver lipid metabolism but increased whole body energy expenditure, likely due to increased β-oxidation in brown adipose tissue and significantly increased voluntary movement, but surprisingly exhibited a form of ataxia." (PMID 23209793, 2012).
bacteremia (1 paper, 2023). "Similarly, the confocal laser microscopy results also showed that P. gingivalis bacteremia significantly inhibited Mfsd2a expression in the microvessels of hippocampus and cortex tissues in the rats of the high-intensity group." (PMID 36631446, 2023). "P. gingivalis bacteremia significantly inhibited Mfsd2a expression in rat brain tissue and BMECs." (PMID 36631446, 2023). "In conclusion, our study indicates that P. gingivalis bacteremia may promote the permeability of BBB in BMECs by the Mfsd2a /Cav-1-mediated transcytosis pathway." (PMID 36631446, 2023).
cerebral infarction (1 paper, 2020). An ischemic condition of the brain, producing a persistent focal neurological deficit in the area of distribution of the cerebral arteries. "For example, in the early stage of cerebral hemorrhage and cerebral infarction, the expression of Mfsd2a decreases, and upregulating its expression can reduce neurological damage." (PMID 32612494, 2020).
cholestasis (1 paper, 2016). Impairment of the bile flow caused by obstruction within the liver, or outside the liver in the bile duct system. "In this study, we also observed that the Mfsd2a+ hepatocytes responded differently in various liver injury models including hepatectomy, CCl4-induced hepatotoxicity, BDL-induced cholestasis and DDC-induced injury." (PMID 27857132, 2016).
Cirrhosis (1 paper, 2019). A chronic disorder of the liver in which liver tissue becomes scarred and is partially replaced by regenerative nodules and fibrotic tissue resulting in loss of liver function. "The low expression of MFSD2A was significantly correlated with poor histological differentiation (P = 0.012), but not with age, sex, tumor size, live cirrhosis, lymph node metastasis, recurrence, serum AFP level, or HBsAg status." (PMID 31584009, 2019).
cognitive decline (1 paper, 2024). "Research on rats with chronic cerebral hypoperfusion has demonstrated that Mfsd2a overexpression can reduce BBB damage and cognitive decline." (PMID 39834810, 2024).
demyelinating disease (1 paper, 2023). A broad group of disorders that affect the myelin sheaths that cover the neurons. "It will be important to determine whether the Mfsd2a/LPC pathway plays a similar role in adult OPC differentiation and myelination and whether LPC supplementation could help to augment remyelination in demyelinating diseases such as multiple sclerosis and in normal aging." (PMID 37104036, 2023).
depression (1 paper, 2025). "As the expression of Mfsd2a prevents BBB disruption by blocking vesicular transport, it is yet to be determined whether n-3 PUFAs regulate Mfsd2a function or expression in depression." (PMID 40725164, 2025).
dermatitis (1 paper, 2026). An inflammatory process affecting the skin. "Epidermal-specific deficiency of Mfsd2a in mice resulted in dermatitis and defective desquamation of the epidermis, and inducible deletion of Mfsd2a in primary mouse keratinocytes in vitro prevented their epidermal stratification." (PMID 41712644, 2026).
diabetes (1 paper, 2024). "Third, the uptake of DHA from circulation may be reduced in diabetes because the expression of Mfsd2a, the transporter responsible for the accretion of DHA, is significantly reduced in the diabetic mouse retina." (PMID 39728692, 2024).
diabetic kidney disease (1 paper, 2023). Progressive kidney disorder caused by vascular damage to the glomerular capillaries, in patients with diabetes mellitus. "Examination of an snRNA expression dataset from a diabetic kidney disease study indicated that Mfsd2a was significantly reduced in patients relative to controls." (PMID 37467896, 2023).
epilepsy (1 paper, 2020). A brain disorder characterized by episodes of abnormally increased neuronal discharge resulting in transient episodes of sensory or motor neurological dysfunction, or psychic dysfunction. "In addition, the role of Mfsd2a in other neurological diseases closely related to BBB, such as Parkinson’s disease, epilepsy, and intracranial infection, is also worthy of investigation." (PMID 32612494, 2020).
fibrosis (1 paper, 2023). the formation of excess fibrous connective tissue in an organ or tissue in a reparative or reactive process. "Liver-specific Mfsd2a deficiency resulted in the development of severe steatohepatitis and fibrosis." (PMID 37463052, 2023).
metastatic tumors (1 paper, 2018). "Since intratumoral blood vessels showed abnormal BBB properties, we analyzed the expression of Mfsd2a in metastatic tumors as well as in the contralateral (opposite) non-injected hemisphere." (PMID 29844613, 2018).
overnutrition (1 paper, 2023). An imbalanced nutritional status resulting from excessive intake of nutrients. "In summary, our findings reveal that uptake of blood-derived LPCs mediated by Mfsd2a constitutes a GR-regulated pathway by which the liver obtains LPCs for maintaining hepatic PCs and that is essential for liver health in the face of overnutrition." (PMID 37463052, 2023). "In this study, we demonstrate that blood-derived LPC transport by Mfsd2a protects the liver from pathologies consequential to overnutrition by stimulating LD formation and supplying the liver with phospholipids." (PMID 37463052, 2023). "Interestingly, GR and PPARα are noncore clock components under circadian control that show enhanced circadian peak activity in overnutrition models, explaining the induction of Mfsd2a expression during the early stages of HFD challenge shown in the current study." (PMID 37463052, 2023).
prostate carcinoma (1 paper, 2017). A carcinoma that arises from epithelial cells of the prostate gland. "Two of the affected genes, MFSD2A and SLC39A1 have been reported as tumor suppressor genes in lung and prostate cancer, respectively, which by definition could carry mutations through the entire length." (PMID 28410231, 2017).
steatosis (1 paper, 2023). Increased lipid within the cytoplasm of cells. "Mfsd2a expression was highly elevated in NASH patients, evident from the intense plasma membrane staining of Mfsd2a in periportal hepatocytes that was absent in the non-NASH patients, with the exception of one patient who had moderate steatosis and inflammation." (PMID 37463052, 2023).
trauma (1 paper, 2021). "Mfsd2a plays a critical role in maintaining BBB permeability, and it was found that overexpression of Mfsd2a after brain injury can be neuroprotective." (PMID 34702292, 2021).
ZIKV infection (1 paper, 2024). "This regard indicated a clear molecular link between ZIKV infection and nervous system disease via Mfsd2a." (PMID 38675970, 2024). "In addition, another study showed that, during ZIKV infection, the protein level of Mfsd2a, rather than the mRNA amount, was perturbed, and the downregulation of Mfsd2a protein responded somewhat to ZIKV." (PMID 38675970, 2024).